EPHB1 (EPH receptor B1)
Diseases named in the same sentence as EPHB1 in open-access papers (continued):
Sharing a sentence is not in itself a finding about the gene and the disease.
tumor (continued). "In addition, we found that 22RV1/PC-3 cells cocultured with macrophages upregulated the percentage of CD206+ macrophages and that tumor cells with si-EPHB1 inhibited the percentage of CD206+ macrophages." (PMID 40548257, 2025). "In contrast, EphB1 appears to play a tumor-suppressive role." (PMID 41200151, 2025). "EphB1 also appears to exhibit a tumor suppressor role in GC." (PMID 39839790, 2024). "Of these, 3 positions were excluded from further studies, L709 due to conservative amino acid change (leucine to isoleucine), and V391 and M23 as they had EPHB1 mutations in single tumours only and were located in non-conserved positions." (PMID 38102712, 2023). "EphB1 has both tumor-suppressing and tumor-promoting roles in some kind of tumors." (PMID 36402751, 2022). "However, EphB1 as a tumor suppressor which mediated growth inhibition, apoptosis, and cycle arrest of EphB1‐expressing AML cells." (PMID 35603962, 2022). "The roles of EphB1/ephrin signaling in tumor microenvironment are less known by now." (PMID 28194092, 2017). "In addition to the tumor-suppressing roles of EphB1 in diverse tumor types, it controversially has tumor-promoting roles." (PMID 28194092, 2017). "In the present study, we report that the loss of EphB1 did not significantly alter tumor growth in the non-radiated cohort (data not shown)." (PMID 25879388, 2015). "However, tumors that were implanted from EphB1−/−Smo mice exhibited a three-fold delay in tumor recurrence after fractionated ionizing radiation compared to allografts harvested from EphB1+/+Smo controls." (PMID 25879388, 2015). "We observed a trend of upregulation of multiple genes (especially EPHB1 and KIF13A) in two PRAD cell lines (22RV1 and PC-3) (p < 0.05), and EPHB1, with the highest mutation frequency, was also significantly upregulated in C4-2, DU145, and C4-2B tumor cells (p < 0.05)." (PMID 40548257, 2025). "Moreover, radiation therapy could be used in combination with knockdown of EphB1 by RNA interference technique to enhance cellular radiosensitization of tumor cells." (PMID 28194092, 2017). "While the loss of EphB1 did not significantly affect tumor growth in the control animals (data not shown), allografted tumors from EphB1−/−Smo mice exhibited a three-fold delay in tumor recurrence after fractionated ionizing radiation compared to allografts harvested from EphB1+/+Smo controls." (PMID 25879388, 2015). "We also note > two-fold increased expression in some members of the Ephrin pathway (EPHA10, EPHB1, EPHB2, EPHB3) that may play key roles in tumor progression, invasion, and immune evasion." (PMID 38704802, 2024). "EphB1 is co-expressed with genes such as ephrin-B1, RND1/2, and SEMA3A, key regulators of neuronal migration, synaptogenesis, and axonal development, indicating that neurodevelopmental pathways may be hijacked to support tumor growth." (PMID 41200151, 2025).
infection (2 papers, 2016 to 2025). The state of being infected such as from the introduction of a foreign agent such as serum, vaccine, antigenic substance or organism. "In contrast, other molecules (VCAM-1, EPHB1, TMEM123, etc.)showed little inhibitory effect on infection within the density range we used." (PMID 41147561, 2025). "To further characterize the role of EPHB1 during myogenic differentiation, we analyzed expression of MYOD and MYOG in C2C12 cells 48 and 72 h respectively after infection, and found an increased number of cells expressing these myogenic markers." (PMID 27446912, 2016).
EPHB1 also shares sentences with these, for which no sentence is quoted: Anxiety (2 papers); hepatocellular carcinoma (2); neuropathic pain (2); adult T cell lymphoma-leukemia (1); Alzheimer disease (1); amyloidosis (1); autism (1); bone cancer (1); breast tumor (1); colorectal tumours (1); endometrioid carcinoma (1); ependymoma (1); frontonasal dysplasia (1); hypertrophic cardiomyopathy (1); insomnia (1); kidney cancer (1); leukemia (1); lung adenocarcinoma (1); lung squamous cell carcinoma (1); major depressive disorder (1); malignant glioma (1); neuroblastoma (1); neurodegenerative disease (1); non-small cell lung carcinoma (1); opioid use disorder (1); osteosarcoma (1); prostate adenocarcinoma (1); ptosis (1); renal papillary cell carcinoma (1); sarcoma (1).
A further 6 diseases each share a sentence with EPHB1 in 1 paper.